IL15 (interleukin 15)
Diseases named in the same sentence as IL15 in open-access papers (continued):
Sharing a sentence is not in itself a finding about the gene and the disease.
tumor (continued). "Unlike IL-15-expressing NK cells, which are translated into significant reductions in disease burden in preclinical models of glioblastoma, IL-21-expressing NK cells potently kill tumor cells." (PMID 40410571, 2025). "Compared with the rapid tumor progression observed in untreated (Utd) mice, tumors in FAP/IL-15 CAR-T-treated mice exhibited minimal or no growth, suggesting enhanced antitumor activity via precise targeting of FAP-positive cells and IL-15 secretion by effector cells." (PMID 41455698, 2025). "Because NK cells are expected to mediate anti‐tumour cytotoxicity without antigen stimulation, in vitro cytotoxicity analyses were performed to evaluate the intrinsic killing capacity of IL‐15 expanded NK cell preparations in parallel with the planned motility analyses." (PMID 40159644, 2025). "Although recombinant human IL-15 (rhIL-15) can up-regulate the expression of DNAM-1 and TIGIT in a dose-dependent manner, DNAM-1 expression is significantly reduced during coculture of NK cells with ovarian cancer cell line spheroids or patient-derived tumor cells." (PMID 40463500, 2025). "Compared with CAR-NK cells co-expressing IL-15, CAR-NK cells co-expressing IL-21 exhibited significantly increased IFN-γ, TNF-α and Granzyme B production, as well as degranulation, in response to CD19+ Raji lymphoma cells, resulting in enhanced cytotoxic activity upon repetitive tumor stimulation." (PMID 40176196, 2025). "Similarly, macrophages in metastatic UVM showed strong enrichment for cytokines like Adiponectin, Prolactin, IL7, IL10, IL15, IL9, IL31, APRIL, Persephin, and IL22, highlighting their role in creating a pro-tumorigenic environment through immune modulation and support of tumor growth." (PMID 39916959, 2024). "In a study of tumour‐bearing mice that were randomly divided into control and HIIT (5 × 10 repetitions, 2 min, 70% Vmax +5 × 9 repetitions, 2 min, 50% Vmax, n = 8) groups, IL‐15 protein expression was increased in the gastrocnemius muscle of HIIT mice after 6 weeks of exercise." (PMID 39601091, 2024). "Given that IL-15 activates and enhances the survival of CD8 T cells and NK cells, anti-prostate stem cell antigen (PSCA) CAR-NK cells engineered with a soluble IL-15 have demonstrated the capability to suppress tumor progression and prolong survival in a mouse model of metastatic pancreatic cancer." (PMID 39633491, 2024). "Notably, exogenous IL-15 did not affect the status of the AKT-mTORC1 or STAT5 pathways in tumor cells." (PMID 38637902, 2024). "Notably, in this study, we did not detect IL-15 in the tumor cell culture supernatants by classical ELISA and it was not increased even in the supernatants collected from tumor cells transfected with IL-15." (PMID 38637902, 2024). "Conversely, our team's anti-PD-L1/IL-15 immunocytokine (LH01), possessing a similar homodimeric structure with the anti-PD-1/IL-15, demonstrated no notable toxicities upon intraperitoneal administration three times at a dosage of 5 mg/kg (100 μg) in MC38 tumor-bearing mice." (PMID 39664443, 2024). "Additionally, IL-15 exerts stronger activation effects on maintenance of CD8+CD44hi memory T cells and immature NK cells (CD56bright NK) compared to IL-2, thus playing a crucial role in antiviral infection and tumor cytotoxicity." (PMID 39160631, 2024). "Thus, the impact of IL-15 on tumor cells should not be overlooked when focusing on its impact on immune cells to more effectively apply IL-15 in cancer therapy." (PMID 38637902, 2024). "Furthermore, self-sufficient production of IL-15 by the NK:BOB1-TCR product showed a clear beneficial TCR-mediated effect in vivo, whereby NK:BOB1-TCR/IL-15 cells were able to clear the tumor and persevere this effect for a longer time compared to NK:BOB1-TCR cells." (PMID 38690288, 2024).
tumor (continued). "Our previous work showed that NK cells briefly stimulated with IL-12, IL-15, and IL-18 become long-lived, memory-like (ML) NK cells with the ability to respond robustly upon restimulation with cytokines and activating receptors, including CD16 engagement with tumor-targeting mAbs." (PMID 38805302, 2024). "In this respect, it will be interesting to examine whether IL-2 and IL-15 have an effect on NKG2D and CD158a-b in MAIT cells, because the cytokines enhance NKG2D expression in different lymphocytes and appear to increase the anti-tumor potential of NK cells." (PMID 38255242, 2024). "While classically thought to be non-cytotoxic, IL-15 increases expression of granzyme (Gzm)A, B and C and may promote ILC1s towards a cytotoxic phenotype against tumours." (PMID 38745765, 2024). "This includes the secretion of cytokines like interleukin (IL): IL-12, IL-15, IL-18, and IL-21 by T-cells redirected for universal cytokine-mediated killing (TRUCKs), can enhance their proliferative activity and reshape the TME while also attracting nearby anti-tumor immune cells." (PMID 38932383, 2024). "However, the mechanisms by which the different modes of action of IL-15 affect tumor cells have not been fully investigated." (PMID 38637902, 2024). "Furthermore, treatment of NK cells with a high concentration of IL-15 has the same effect in educated and uneducated NK cells, indicating that NK cell dysfunction in a tumor environment is independent of education." (PMID 39196934, 2024). "This therapeutic approach not only effectively facilitates the expression of IL-15, but also significantly enhances intracellular reactive oxygen species (ROS) levels, induces immunogenic cell death (ICD), thereby effectively suppressing tumor growth and recurrence." (PMID 39543114, 2024). "The expression level of IL-15 in tumor cells did not affect their proliferation." (PMID 38637902, 2024). "Further, GT-00AxIL15 exerted enhanced anti-tumor cytotoxicity compared to its parental mAb GT-00A and an untargeted MOPCxIL15 isotype control, which is mediated by TA-MUC1-targeting in combination with increased effector cell-mediated cytotoxicity induced by the IL-15 modules." (PMID 38338686, 2024). "The development of these and additional KO tumor models will also allow exploring the potential of novel treatements beyond ICB, such as IL-15 and IL-12 immunocytokine therapies, where the presence of these tumor-cell intrinsic gene defects may add clinical benefit via NK cells." (PMID 38427670, 2024). "Moreover, IL-15 and CX3CL1 plasma levels were positively correlated with markers of inflammation and high tumor burden (fibrinogen, lactate dehydrogenase, C-reactive protein, cell-free DNA, CXCL9) at pre-lymphodepletion, a biochemical makeup that has been associated with ICANS." (PMID 38833312, 2024). "As a pleiotropic cytokine with an immune-potentiating effect on both T cells and natural killer (NK) cells, IL-15 armoring has also been reported to improve the antitumor activity of human CAR-T cells targeting multiple antigens across both blood and solid xenograft tumor models." (PMID 37564658, 2023). "However, FITC CAR T cells expanded in IL-7 and IL-15 rather than IL-2 did not demonstrate enhanced tumour control." (PMID 37291434, 2023). "Interestingly, the absence of CD8+ T cells led to a better tumor controle when no IL-15 was present." (PMID 37923822, 2023). "In addition, the protein level of IL15 and the IL15 secretion were also increased in KYSE150 and AKR cells with PES1 knockdown, which was further confirmed in subcutaneous tumor samples via western blotting." (PMID 36959575, 2023). "Despite cyto-IL-15 alone slowing tumor growth, it did not lead to complete regression of any of the injected tumors (same as in the single flank challenge experiment), but it generated a small abscopal response in the distal (left flank) uninjected site with a 25% complete rejection." (PMID 37465665, 2023).
tumor (continued). "Finally, we did not analyze such serum cytokines as IFN-gamma, IL-2, IL-15, and IL-12, which can increase tumor cell class I MHC expression and sensitivity to lysis by CTLs or tumoricidal capacity of NK cells." (PMID 37894429, 2023). "We next investigated the antitumoral activity of biNV-IL-15 in different tumor models (4T1, CT26, and B16F10-OVA) to assess the adaptability and flexibility of biomimetic nanovaccine-mediated spatiotemporal integration of multivalent IL-15 self-transpresentation and tumor antigen presentation." (PMID 37875481, 2023). "However, similar to TRAMP-C1 tumors, only the combination treatment with cyto-IL-15 and ADU led to complete tumor regression (97% volume reduction), had the greatest impact on survival (99 days, p < 0.0001) and cured 7 out of 12 mice (58%) with TRAMP-C2 tumors." (PMID 37465665, 2023). "IL-15 alone failed to suppress tumor recurrence with unsatisfactory survival." (PMID 37875481, 2023). "Furthermore, IL-15 production by CD24+CD29+EpCAM+ epithelial cells was higher in PyMT tumors than in normal tissue and the deletion of tumor-expressed IL-15 resulted in a decrease of ILC1s, a downregulation of granzyme B and C expression, and a reduced tumor control." (PMID 36115839, 2022). "The findings showed that in the absence of IL-15, tumor exosomes induce a significant reduction in NKG2D expression, but adding IL-15 could abolish the effect of exosomes and restore NKG2D to the baseline levels." (PMID 35031075, 2022). "Herein, using CD19-specific CAR, our results indicate that IL-15 combined with IL-15Ra reduced the expression of CD132 compared to conventional CAR-T and IL-15 armored CAR-T cells, leading to the relatively highest survival rate and keeping liver healthier in tumor-treated mice." (PMID 36167591, 2022). "In addition, triple-gene-edited CD38KO iPSC-derived NK cells, co-expressing non-cleavable CD16a and IL-15/IL-15R fusion protein, have achieved desirable results in the tests of their in vivo persistence and tumor-directed cytotoxicity." (PMID 36428748, 2022). "It was reported that supplementation of IL-15 alone can lead to reduced exhaustion marker expression, an increase of anti-apoptotic properties providing similar performance in stimulating CAR-T cell expansion, persistence in vivo and tumor-lysis functions in vitro." (PMID 36172343, 2022). "Therefore, Chou and colleagues next generated a conditional transgenic breast cancer mouse model in which IL-15 production was specifically ablated within the transformed tumour cells, but not in healthy tissue." (PMID 35768418, 2022). "Yet, again and with all the doses tested, the non‐targeted TPA did not produce any IL15 mRNA expression in the tumours and normal organs, and IL15 expression in the healthy tissues from the RGD4C.TPA.IL15IgK group, was similar to that of non‐targeted TPA (Fig EV4A)." (PMID 35758207, 2022). "had previously shown that tumor-specific tolerant T cells, which failed to proliferate in vitro, could be rescued by incubation in medium containing high-dose IL15 (or, less efficiently, IL2)." (PMID 33796916, 2021). "Notably, transpresented IL-15 alone, but not PD-1 blockade, significantly reduced tumor burden in all treated TIL-PDX-LUAD animals." (PMID 34081628, 2021). "We and others have shown that a short-term stimulation through IL12, IL15, and IL18 receptors induce NK cells with an enhanced ability to produce IFNγ, TNF, and MIP1α in response to cytokines, activating receptors triggering or restimulation with tumor targets." (PMID 34187852, 2021). "Moreover, it suggests that fractalkine and IL-15 synergise to promote NK cell migration and indicates that these two alone are not the soluble factors in OAC omentum which impede NK cell migration towards tumour in our ex vivo assays." (PMID 35008227, 2021).
tumor (continued). "In the context of IL-15 immunotherapy, pharmacological targeting of STAT3 may thus be preferably only some time following the localization and priming-enhanced adaption of NK cells to hypoxic sites such as the tumor microenvironment." (PMID 33782423, 2021). "Notably, IL-15 alone, without PD-1 blockade, significantly reduced tumor burden in all treated LUAD-SIS-PDX animals." (PMID 34025641, 2021). "The inconsistency of increased IL-15 levels acting both as a positive or negative marker in regard to tumor progression and survival outcome, could be explained by the role of dendritic cells (DCs) and their effect on the Immune system." (PMID 32929618, 2021). "Moreover, cytotopic modification of the purified IL-15 results in a highly active protein that can significantly prolong mouse survival by delaying tumor growth without any side effects." (PMID 34778376, 2021). "Although activated CAR T cells produce cytokines, such as interleukin-2 (IL-2), production decreases after repeated exposure to tumor cells, and some cytokines that are important for T cell effector function, such as IL-12 and IL-15, are either produced at low levels are not at all by T cells." (PMID 34177932, 2021). "However, IL-15 preparations administered as monotherapy were ineffective, due to actions of immunological checkpoints and due to the lack of tumor specific targeting by NK cells." (PMID 32508818, 2020). "A rational approach is to use tumor-localized implants loaded with tumor-specific lymphocytes that contain additional T cell-activating biologicals (such as activating anti-CD3, anti-CD28, and anti-CD137 antibodies) and T cell stimulatory cytokines (like IL-2 or IL-15)." (PMID 32942725, 2020). "Stromal cells can mediate immune-suppression and protect tumor cells from cytotoxicity via secretion of soluble factors including immune suppressive mediators such as IL-10, TGF-β and PGE2 or growth factors such as stem cell factor (SCF), IL-7, IL-15, CXCL-12 among others." (PMID 32483120, 2020). "Furthermore, our research team found that the destruction capacity of oncolytic adenovirus armed with IL-15 on tumor cells was stronger than that of the control virus (data not shown)." (PMID 32587256, 2020). "As expected, the tumor-bearing DCs co-cultured with cryo-thermal macrophages were highly matured, as demonstrated by the increased percentage of CD11c+CD86+MHC II+ DCs along with the higher relative expression of IL-6, TNF-α, CXCL10, IL-1β, IL-12p40, and IL-15 mRNA." (PMID 30833570, 2019). "Interestingly, IL-15 augmented DNT function by increasing the expression of effector molecules on DNTs, potentially reducing the activation threshold required for the anti-tumor activity of DNTs." (PMID 30670085, 2019). "Moreover, blockade of IL-4 resulted in overexpression of pro-inflammatory cytokines (CXCL10, IL-1β, IL-15, IL-10 and IL-6) and lower expression of immunosuppressive molecules (Foxo3, IDO1 and PD-L1) as compared to cryo-thermal eosinophils + tumour-bearing DCs group." (PMID 31519961, 2019). "Notably, IL-15 induces a rapid expansion of memory CD8+ T cells, thus favoring anti-tumor activity." (PMID 32010130, 2019). "The beneficial action of IL-15 in vivo administration was mediated exclusively by the transferred cells and not by the host cells since there was no decrease in the tumor burden in mice administered only with IL-15, consistent with what demonstrated previously." (PMID 31699153, 2019). "In comparison, IL-15 was dosed at 2 μg/mouse without tumor shrinking effect." (PMID 29769573, 2018). "Additionally, an increase in tumor CD8 cells was observed in mice treated with KD033-surrogate compared to the non-targeted IL-15 fusion antibody." (PMID 30400822, 2018). "IL-2, IL-15 and IL-15 expanded TIL from primary solid cancer and metastatic lesions promotes the cultivation of a focused T-cell product directed against the patient’s autologous tumor cells and offers a viable treatment modality for patients with solid cancer." (PMID 30400835, 2018).
tumor (continued). "Briefly, during the experiment, dCAR-T cells could release significant levels of cytokines only in the presence of cognate tumor cells expressing both CEA and MSLN, including 751 pg/mL IL-2, 9297 pg/mL IFNγ, 1777 pg/mL TNFα, 732 pg/mL IL-4, 8991 pg/mL IL-13, and 99 pg/mL IL-15." (PMID 30103775, 2018). "Finally, co-expression of IL-15 did not result in elevated regulatory T cell levels in tumor environment measured by flow cytometry." (PMID 30452438, 2018). "To further investigate whether IGF-1 facilitate tumor growth in our study, we sorted CD45+ CD11b+ Gr-1+ CD215+ and CD45+ CD11b+ Gr-1+ CD215− cells from the spleen of tumor-bearing mice and cultured them with A549-GFP-luciferase cells with IL-15 or IL-15 plus anti-IGF-1 antibody." (PMID 29255466, 2017). "Furthermore, Cox proportional hazard regression analysis revealed that tumor size (p = 0.012, p = 0.623), tumor thrombus (p = 0.011, p = 0.015), UCSF criteria (p = 0.471, p = 0.013), and recipient IL-15 rs10519613 genotype (p = 0.039, p = 0.008) were independent factors of predicting DFS and OS." (PMID 29162948, 2017). "Additionally, IL-15 increases the anti-tumor activity of murine αβ T cells in mice but its effect on the in vivo anti-tumor activity of human Vγ2Vδ2 cells has not been assessed." (PMID 28239463, 2017). "However, in mice, CD8 αβ T cells expanded ex vivo using IL-15 or IL-7/IL-15 rather than IL-2, mediate increased tumor immunity." (PMID 28239463, 2017). "Notably, tumor cell eradication in trastuzumab/IL-15-treated HTM is not only achieved by NK-cell activation but also by a stimulation and increased infiltration of CD33+ myeloid cells (e.g., macrophages)." (PMID 27835865, 2017). "Performing a 4-hour cytotoxicity assay with migrated cells from a 3-hour migration assay, purified γδ T cells and NK cells attracted by secreted factors of IL-15 DCs showed a significantly higher killing capacity against tumor cells as compared to their non-migrated counterparts." (PMID 28099143, 2017). "However, adoptive transfer of Vγ2Vδ2 T cells expanded with IL-15 did not result in improved tumor immunity compared to those expanded with IL-2." (PMID 28239463, 2017). "But no enhanced or reduced tumor growth was observed in mice when human IL-15 was used." (PMID 29255466, 2017). "Thus, our results suggest that CD215+ myeloid cells respond to IL-15 and promote cancer progression, and IGF-1 may be an important candidate that IL-15 facilitates tumor growth." (PMID 29255466, 2017). "Importantly, PD0325901 did not affect the anti-tumor activity of NK cells that had been exposed to a combination of IL-15 and IL-18." (PMID 27563819, 2016). "Together with IL-15, which is a critical factor for development, proliferation and activation of natural killer cells and CD8+ memory T cells, it may effectively contribute to fight the tumor." (PMID 27809856, 2016). "Thus, our data suggest that IL-15 and IL-18 cytokines could be utilized in combination with BRAF/MEK inhibitors to sustain and/or activate NK cell anti-tumor potential in vivo." (PMID 27563819, 2016). "The results of the present study clearly show that IL-15 DCs, but not conventional IL-4 DCs, can induce an activated phenotype in NK cells and enhance NK cell cytotoxicity against both NK-sensitive as well as NK-insensitive tumor cells." (PMID 25951230, 2015). "In addition, histological analysis revealed that the tumor destruction in IL-15 TG/MT mice was absent when these NK1.1+ cells were absent." (PMID 25879689, 2015). "IL-15 KO/MT spleen or tumor CD8 T cells produced little to no IFNγ (data not shown)." (PMID 25879689, 2015). "Since this effect was not seen in the CD16/32+ populations, IL-15 may be important in regulation of IL-6 in T cells or other CD16/32− cells in the tumor microenvironment." (PMID 24416335, 2014).